SBDSP1 (SBDS pseudogene 1 )
Synonyms: SBDSP
Gene: Long non-coding RNA gene on chromosome 7 (72,829,374 to 72,837,399, forward strand). Ensembl gene ENSG00000291152.
Diseases named in the same sentence as SBDSP1 in open-access papers:
SBDSP1 is named in the same sentence as 3 diseases in open-access papers, as found by Europe PMC text mining. Sharing a sentence is not in itself a finding about the gene and the disease. The quoted sentences say what the papers report.
colon cancer (1 paper, 2020). "One group showed that lncRNA SBDSP1 is elevated in colon cancer tissues and further correlates with differentiation, invasion depth, TNM stage, and survival time in colon cancer patients." (PMID 33246471, 2020).
colorectal cancer (1 paper, 2021). A primary or metastatic malignant neoplasm that affects the colon or rectum. "The pseudogene‐derived lncRNA SBDSP1 has been shown to suppress tumor growth and invasion and is related to poor outcomes in colorectal cancer." (PMID 33660378, 2021).
SBDSP1 also shares sentences with these, for which no sentence is quoted: tumor (1 paper).